NFAT5 (nuclear factor of activated T cells 5)
Diseases named in the same sentence as NFAT5 in open-access papers (continued):
Sharing a sentence is not in itself a finding about the gene and the disease.
epilepsy (1 paper, 2021). A brain disorder characterized by episodes of abnormally increased neuronal discharge resulting in transient episodes of sensory or motor neurological dysfunction, or psychic dysfunction. "Increased NFAT5 expression induced by inflammatory signals aggravated blood–brain barrier injury, neuroinflammation, and neuron hyperexcitability-induced epilepsy." (PMID 33776905, 2021). "XIST and NFAT5 expression was increased while miR-29c-3p expression was decreased in epilepsy rat models and LPS-stimulated CTX-TNA2 cells." (PMID 33776905, 2021). "XIST expression and NFAT5 protein level was increased, whereas miR-29c-3p expression was decreased in the epilepsy rat model and LPS-treated CTX-TNA2 cells." (PMID 33776905, 2021). "Furthermore, XIST, NFAT5, and miR-29c-3p effect on epilepsy rat model were not elucidate." (PMID 33776905, 2021).
hemangioma (1 paper, 2010). A benign vascular lesion characterized by the formation of capillary-sized or cavernous vascular channels. "Furthermore, down-regulation of Nfat5 (nuclear factor of activated T-cells 5) parallels a decrease in VEGF’s receptor VEGFR1 and an increase in VEGFR2 in hemangioma endothelial cells." (PMID 21210965, 2010).
hemophagocytic lymphohistiocytosis (1 paper, 2022). "We describe two cases of pediatric Mexican patients with rare heterozygous missense variants in NFAT5 and EBV susceptibility, a school-age girl with chronic-active infection of the liver and bowel, and a teenage boy who died of hemophagocytic lymphohistiocytosis." (PMID 36238298, 2022).
HIV-1 infection (1 paper, 2012). The type species of lentivirus and the etiologic agent of acquired immunodeficiency syndrome (AIDS). "We also investigated whether HIV-1 infection is capable of inducing NFAT5 mRNA synthesis by infecting MDM with live or heat-inactivated R5-tropic representatives of subtype B (HIV-1Bal), C (HIV-198IN22), or E (HIV-192TH64)." (PMID 22496647, 2012). "Free virus levels were then measured in culture supernatants from MDM transfected with NFAT5-specific siRNA or GFP control siRNA at days 6, 9 and 12 post-HIV-1 infection to measure the impact of NFAT5 inhibition on MTb-induced HIV replication." (PMID 22496647, 2012).
hydrops (1 paper, 2023). "Furthermore, the modulation of NFAT5 might be a therapeutic avenue for patients suffering from hydrops in keratoconus to prevent massive corneal edema and to avoid surgical therapy." (PMID 36869067, 2023).
ichthyosis (1 paper, 2021). Disorders of cornification that are characterized by visible scaling and/or hyperkeratosis of most or all of the skin. "Under pathophysiological and experimental in vitro conditions, such as in epidermis from Ichthyosis patients and of sun-exposed persons, NFAT5 was predominantly expressed in suprabasal KCs." (PMID 34956208, 2021).
invasive ductal breast carcinoma (1 paper, 2015). The most common type of invasive breast carcinoma, accounting for approximately 70% of breast carcinomas. "Ubiquitous expression of NFAT isoforms in mammalian tissues has been described, and mainly two isoforms, NFAT1 and NFAT5, have been reported as overexpressed in human invasive ductal breast carcinomas." (PMID 25928084, 2015).
kidney cancer (1 paper, 2025). Primary or metastatic malignant neoplasm involving the kidney. "In Kidney cancer, high NFAT5 expression was significantly associated with better OS (p = 0.01; HR = 0.67 [0.50-0.91]), suggesting a protective role of NFAT5 in kidney tumor patients." (PMID 41584586, 2025). "This observed switch to a repressive function provides a mechanistic explanation for our key clinical finding: high NFAT5 expression correlates with significantly improved survival in kidney cancer patients." (PMID 41584586, 2025). "Furthermore, Overall Survival (OS) analysis using OncoDB data revealed differential prognostic value of NFAT5 in liver and kidney cancer." (PMID 41584586, 2025).
laryngeal squamous cell carcinoma (1 paper, 2022). A squamous cell carcinoma that arises from the larynx. "Among these 12 prognostic crlncRNAs, the lncRNA of SNHG16 was upregulated in laryngeal squamous cell carcinoma tissues (LSCC) by regulating the miR-140-5p/NFAT5/Wnt/β-catenin pathway axis, which may possibly provide a novel method for HNSCC treatment." (PMID 36568234, 2022).
leishmaniasis (1 paper, 2021). Infectious disease that is transmitted through the bite of hematophagous female phlebotomine sand flies. "SHP-1 is a protein phosphatase which dephosphorylates NFAT5 and therefore regulates NFAT5 activity in response to Leishmaniasis." (PMID 35126456, 2021). "To conclude we posit that computational modeling of IL12 and IL10 reciprocity through NFAT5 in Leishmaniasis helps us to understand the signaling mechanism responsible for parasite survival." (PMID 35126456, 2021). "Thus, the system’s biological approach provides us with the necessary lead in a specific reconstructed biological network and by modulating NFAT5; we might be able to find a better therapeutic for treating Leishmaniasis." (PMID 35126456, 2021).
lower respiratory tract infections (1 paper, 2022). "A previous study demonstrated that host transcriptome profiles helped build a host transcriptional classifier (NFAT-5, ZC3H11A, and PRRC2C) for diagnosing lower respiratory tract infections with an AUC of 0.88 (95% CI, 0.75-1.00)." (PMID 36483456, 2022).
lung carcinoid tumor (1 paper, 2021). A neuroendocrine neoplasm that arises from the lung. "In Bhattacharjee’s dataset, the mRNA expression levels of NFAT5 in small cell lung carcinoma and lung carcinoid tumor were significantly higher than those in the corresponding normal lung tissues, with their fold changes of 2.175 and 2.421, respectively." (PMID 34257525, 2021).
lupus nephritis (1 paper, 2023). Glomerulonephritis in the context of systemic lupus erythematosus. "In individuals with lupus nephritis (LN), it has been observed that NFAT5 expression is increased, which is positively correlated with the expression of inflammatory cytokines and the severity of proteinuria." (PMID 37287987, 2023).
Meniere disease (1 paper, 2023). A disease of the inner ear (labyrinth) that is characterized by fluctuating sensorineural hearing loss; tinnitus; episodic vertigo; and aural fullness. "Furthermore, search for C. robusta NFAT5 led to the identification of FAM136A, a mitochondrial protein conserved across metazoans whose human orthologue shows a correlation with Meniere’s disease, an inner ear problem with an autoimmune condition." (PMID 37600818, 2023).
metastatic disease (1 paper, 2024). "In conclusion, the presented work identified the seven genes EMILIN3, MTA1, SV2B, TMPRSS6, ACVR1C, NFAT5 and SMC3 associated with the formation of colorectal BM during the course of disease but not with liver metastasis or non-metastatic disease." (PMID 38558282, 2024).
middle ear cholesteatoma (1 paper, 2024). "The interaction network analysis of the two most upregulated miRNAs (hsa-miR-21-5p and hsa-miR-142-5p) and the three most downregulated miRNAs (hsa-miR-508-3p, hsa-miR-509-3p, and hsa-miR-211-5p) identified TGFBR2, MBNL1, and NFAT5 as potential key target genes in middle ear cholesteatoma." (PMID 38890701, 2024). "The interaction network of the the 2 most upregulated (hsa-miR-21-5p and hsa-miR-142-5p) and 3 most downregulated (hsa-miR-508-3p, hsa-miR-509-3p and hsa-miR-211-5p) miRNAs identified TGFBR2, MBNL1, and NFAT5 as potential key target genes in middle ear cholesteatoma." (PMID 38890701, 2024).
Myositis (1 paper, 2018). "The goal of this study was to investigate NFAT5 physiology in unaffected myoblasts exposed to cytokine or hyperosmolar stress and in myositis." (PMID 29515464, 2018). "As NFAT5 is a core protein to myogenesis, our findings may help further our understanding of impaired muscle regeneration in myositis." (PMID 29515464, 2018). "This disturbed myogenic NFAT5 physiology could possibly explain deleterious effects on muscle regeneration in myositis." (PMID 29515464, 2018).
pancreatic ductal adenocarcinoma (1 paper, 2024). An infiltrating adenocarcinoma that arises from the epithelial cells of the pancreas. "NFAT5 facilitates pancreatic ductal adenocarcinoma cell survival by contributing to the Warburg effect through the transcription of PGK1." (PMID 39822413, 2024).
Peritoneal Fibrosis (1 paper, 2012). Disorder characterized by a wide range of structural changes in PERITONEUM, resulting from fibrogenic or inflammatory processes. "NFAT5 in turn upregulates MCP-1, likely in combination with NF-κB, and thus may participate in the development of peritoneal fibrosis during CAPD." (PMID 22619484, 2012).
pituitary tumor (1 paper, 2013). A benign or malignant neoplasm affecting the pituitary gland. "β-catenin, NFAT5 and JNK proteins showed no expression in normal pituitaries and in any of the pituitary tumor subtypes." (PMID 23638078, 2013).
pneumonitis (1 paper, 2022). An inflammatory process affecting the lung parenchyma. "Although the role of a low-salt diet in clinical cancer patients is unknown, our data suggest that a low-salt diet, through the downregulation of NFAT5-mediated inflammasome complex, reduces pneumonitis and systemic circulating frequency pro-inflammatory CD4+T cells." (PMID 35741331, 2022).
pulmonary hypertension (1 paper, 2021). Increased pressure within the pulmonary circulation due to lung or heart disorder. "Consequently, we tested whether mitochondrion-specific scavenging of ROS prevents out-of-proportion pulmonary hypertension in hypoxia-exposed Nfat5(SMC)−/− mice." (PMID 34943801, 2021).
Rectal prolapse (1 paper, 2025). Protrusion of the rectal mucous membrane through the anus. "Nonetheless, compared with the Il10–/–Nfat5+/+ mice, the Il10–/–Nfat5+/– mice had higher DAI scores, more frequent rectal prolapse, and more severe shortening and microscopic pathology of the colon." (PMID 40663408, 2025). "The experiments ended before any difference in body weight was observed (data not shown) because severe rectal prolapse was observed in some Il10 and Nfat5 double-KO (Il10–/–Nfat5+/–) mice." (PMID 40663408, 2025).
serous carcinoma (1 paper, 2021). "In addition, elevated cytoplasmic NFAT5 expression was significantly associated with low grading of serous carcinoma (p<0.001)." (PMID 34631538, 2021). "Taking clinical aspects into account, the presence of NFAT5 as an inactive transcription factor in EOC patients was linked to prognostically favorable characteristics, as a high cytoplasmic protein abundance correlated significantly with low FIGO stages and low grading of serous carcinoma." (PMID 34631538, 2021).
Stroke (1 paper, 2024). Sudden impairment of blood flow to a part of the brain due to occlusion or rupture of an artery to the brain. "Although the overall protective impact of endothelial NFAT5 on the stroke severity may clearly be deduced from our data, the delineation of the origin of the observed effects was challenging." (PMID 39710754, 2024). "Collectively, loss of endothelial Nfat5 resulted in expanded infarct sizes after brain I/R without specifically affecting vascular integrity, angiogenic activation or stroke-associated neuroinflammation." (PMID 39710754, 2024). "Moreover, a NFAT5-dependent neuroprotective mechanism originating from the BEC population appears unlikely given the unchanged degree of neuronal cell death in the late acute phase upon stroke." (PMID 39710754, 2024). "Thus, Nfat5 deficiency in BEC may not substantially affect the overall cell death in the late acute phase after stroke." (PMID 39710754, 2024). "However, the decline of cerebral microvessels due to stroke was not different in Nfat5(EC)−/− versus Nfat5fl/fl mice (Supplement S4A, B)." (PMID 39710754, 2024).
vitiligo (1 paper, 2025). Generalized well circumscribed patches of leukoderma that are generally distributed over symmetric body locations and is due to autoimmune destruction of melanocytes. "In active vitiligo, both Foxp3 and NFAT5 transcripts are significantly downregulated, suggesting a potential link between NFAT5 deficiency and Treg dysfunction." (PMID 40421201, 2025).
tumor (54 papers, 2013 to 2026). "NFAT5 is highly expressed in exhausted tumor-induced CD8+ T cells and is associated with decreased tumor control." (PMID 40421201, 2025). "NFAT5 is upregulated by hyperosmolarity caused by local inflammatory reaction e.g. induced by tumor growth." (PMID 38558282, 2024). "Bioluminescent images and hematoxylin and eosin (H&E) staining demonstrated that loss of NFAT5 significantly abrogated EGFR-driven tumor growth and enhanced the sensitivity of tumors to TMZ." (PMID 37429858, 2023). "In contrast, NFAT5-deficient macrophages exhibit reduced pro-inflammatory function, resulting in enhanced tumor growth in Lewis lung carcinoma and ID8 ovarian carcinoma models." (PMID 30873159, 2019). "It is implicated in the relationship of NFAT5 expression in tumor cells and tumorigenesis in terms of tonicity-dependent manners." (PMID 30873159, 2019). "Knockdown of NFAT5 lead to impaired proliferation of tumor cells caused by an aberrant Warburg effect." (PMID 31827081, 2019). "Here, we found that all five transcription factors are highly expressed in tumor tissue, and the expression of NFAT5 is negatively associated with prognosis." (PMID 31827081, 2019). "Especially the designated NFAT5 target gene HSP70 has been implicated in tumor cell proliferation, differentiation, and metastasis in a wide variety of cancers." (PMID 25152734, 2014). "Notably, several target genes—including WNK1, CDK6, NCOA3, and NFAT5—are functionally linked to key oncogenic processes such as tumor growth, proliferation, and metastasis (eFigure 7A in Supplement 1)." (PMID 40737022, 2025). "Even though the exact underlying mechanism that drives aberrant expression of NFAT5 in tumor tissues remains elusive, the advent of selective COX2 inhibitors as anti-cancer therapies could be a useful tool for EnCa." (PMID 38612478, 2024). "Additionally, the downregulation of NFAT5 in LUAD in the UALCAN database was supported by the results that higher mRNA of NFAT5 in LUAD was associated with tumor stage 2 and a better outcome." (PMID 34257525, 2021). "Furthermore, NFAT5 acts as a tumor suppressor in HBV-associated HCC tissues by suppressing DARS2 expression." (PMID 29052520, 2017). "While outside the scope of this study, other NFAT family members, such as NFAT5, have been implicated in KRAS inhibitor resistance through roles in EMT and tumor plasticity." (PMID 40856537, 2026). "Macrophages in the tumor microenvironment induce NFAT5 expression in A549 LUAD cells, contributing to cisplatin resistance, cell migration, and invasion." (PMID 40421201, 2025). "Molecular mechanistic studies using transgenic mice have demonstrated a critical role of NFAT5 in this high-salt-mediated tumor-specific effector phenotype switch." (PMID 40563574, 2025). "These helicases interact with CDK-9, enhancing neoplastic cell proliferation, positioning NFAT5 as a key regulator of tumor growth and invasiveness." (PMID 40421201, 2025). "High expression of NFAT5 levels in renal cell carcinoma has been correlated with various clinicopathological features, including tumor stage, grade, and metastasis." (PMID 38612478, 2024). "RNA data revealed that NFAT5 transcript levels were also significantly higher in G3 (aggressive) tumor tissues (*, p = 0.0130) compared to low-grade G1 tumor tissues." (PMID 38612478, 2024). "This suggests NFAT5’s potential role in the aggressiveness and progression of tumor pathophysiology." (PMID 38612478, 2024). "NFAT5, as a protective factor, is well studied; however, its role in endometrium and tumor progression and metastasis is still in its infancy." (PMID 38612478, 2024). "In particular, 63.3% of (31/49) tumor samples with high NFAT5 expression exhibited a strong p-EGFR staining." (PMID 37429858, 2023). "In line with this in vitro evidence, our murine studies have also demonstrated that NFAT5 expression in tumor-infiltrating CD4+T cells was increased in the HS diet cohort more than in the NS and LS diet cohorts." (PMID 35741331, 2022).